KL (klotho)
Diseases named in the same sentence as KL in open-access papers (continued):
Sharing a sentence is not in itself a finding about the gene and the disease.
lung fibrosis (12 papers, 2017 to 2026). "Importantly, senolytic drug also increased KL in the urine of patients with idiopathic pulmonary fibrosis (IPF), a disease linked to cellular senescence." (PMID 40018267, 2025). "Our opinion is that the evidence is limited, and further investigation to define whether deficiency of lung Klotho and Wnt/β-catenin signaling plays a role in pulmonary fibrosis and emphysema is required." (PMID 32188018, 2020). "Conversely, transgenic mice overexpressing Klotho are protected from the development of pulmonary fibrosis after bleomycin." (PMID 40554265, 2025). "Analysis of a large IPF RNA-seq database has identified Klotho as a key regulator and recombinant Klotho is effective in preventing lung fibrosis in the bleomycin mouse model." (PMID 40554265, 2025). "Previously, in idiopathic pulmonary fibrosis and mouse pulmonary fibrosis models, klotho was found to decline, implying that it participated in pulmonary fibrosis." (PMID 36724065, 2023). "Recently, Huang also reported that klotho antagonizes pulmonary fibrosis by suppressing pulmonary fibroblast activation, migration, and extracellular matrix production." (PMID 36724065, 2023). "Previously, the declines of KL in serum from IPF patients as well as in several mouse pulmonary fibrosis models imply the involvement of KL in the pathogenesis of pulmonary fibrosis." (PMID 32244228, 2020). "In the light of bioinformatic prediction and experimental validation, this study presented extensive characterization of the anti-fibrotic role of KL in pulmonary fibrosis, rendering it a promising target of therapeutic intervention for patients with IPF." (PMID 32244228, 2020). "Interleukin-18 (IL-18) could downregulate the anti-aging protein Klotho, promoting fibroblast senescence in pulmonary fibrosis." (PMID 41522514, 2026). "Overall, KL appears to be a vital regulator during pulmonary fibrosis." (PMID 32244228, 2020). "Further clues of the anti-fibrotic potential of KL in the lung include Kl-heterozygous hypomorphic allele mice displayed exacerbated asbestos- and bleomycin- induced pulmonary fibrosis, and that both recombinant KL (rKL) supplementation and Kl-overexpression attenuated pulmonary fibrosis response." (PMID 32244228, 2020). "We further enhanced the validity of our prediction by showing two genes predicted to be functionally related with KL could effectively mediate its activity against pulmonary fibrosis." (PMID 32244228, 2020). "As demonstrated in several experiments on murine asthma models and human bronchial epithelial cells, klotho may counteract the remodeling of airways and prevent lung fibrosis by interfering with TGF-β1 and VEGF." (PMID 28912623, 2017). "In the lungs, low Klotho may contribute to the development of idiopathic pulmonary fibrosis." (PMID 32188018, 2020). "In an idiopathic pulmonary fibrosis clinical trial (NCT02874989), D&Q improved physical function and increased urinary α-Klotho, suggesting that D&Q could modulate Klotho levels." (PMID 40573218, 2025). "Furthermore, Klotho can inhibit signaling pathways such as Wnt/β-catenin and TGF-β1, reducing lung fibrosis in asthma patients and improving lung function." (PMID 38287280, 2024).
ovarian carcinoma (12 papers, 2013 to 2025). A malignant neoplasm originating from the surface ovarian epithelium. "The expression of Klotho can be affected by hypermethylation of the KL gene promoter, as observed in pancreatic and ovarian cancers, which is associated with a poor prognosis." (PMID 40004457, 2025). "A meta‐analysis showed that the F allele of the F352 V polymorphism in Klotho gene protects against breast and ovarian cancer susceptibility and is associated with an overall risk of cancer in BRCA1 mutation carriers." (PMID 35841322, 2023). "Increased Klotho expression has also been associated with beneficial and detrimental outcomes in ovarian cancer patients." (PMID 34577143, 2021). "KL suppresses a tumor-associated inflammatory response in mice with ovarian cancer, thereby contributing to a more favorable outcome." (PMID 33520985, 2020). "KL expression is lower in ovarian cancer and is associated with decreased survival." (PMID 33520985, 2020). "However, Klotho expression is associated with epithelial ovarian cancer progression, and the protein may serve as an independent marker for ovarian cancer prognosis." (PMID 23516476, 2013). "A marked reduction in KL expression was observed in patients’ samples, while the overexpression of KL notably suppressed the proliferation of ovarian cancer cells in vitro." (PMID 40004457, 2025). "Furthermore, in lung and ovarian cancers, KL overexpression increases sensitivity to cisplatin chemotherapy, enhancing treatment efficacy and reducing drug resistance." (PMID 40004457, 2025). "In summary, Klotho serves as a powerful tumor suppressor in human ovarian cancer cells." (PMID 40004457, 2025). "KL could be a prognostic biomarker for several cancers, such as ovarian cancer and head and neck squamous carcinomas." (PMID 36091132, 2022). "Results regarding the role of KL in ovarian cancer are controversial." (PMID 33520985, 2020).
pancreatic cancer (12 papers, 2015 to 2024). "Downregulation of Klotho was found in several cancers, such as pancreatic cancer and other type of tumors." (PMID 39199335, 2024). "Overexpression of Klotho, or therapy with s-Klotho, inhibited the growth of pancreatic cancer cells." (PMID 35903083, 2022). "We aimed to study the role of the anti-aging protein klotho and its secreted isoform, sKL, in pancreatic cancer." (PMID 34944918, 2021). "In vitro, klotho reduces growth of pancreatic cancer cells, and inhibits the IGF-I and bFGF pathways." (PMID 34944918, 2021). "Bioinformatics analyses revealed a correlation between the survival of PDAC patients, and levels of klotho expression and DNA methylation, and demonstrated a unique hypermethylation pattern of KLOTHO in pancreatic tumors." (PMID 34944918, 2021). "Three in vivo models, including a novel genetic mouse model and bioinformatics analyses, indicated klotho as a tumor suppressor in pancreatic ductal adenocarcinoma, and unveiled a unique klotho DNA hypermethylation pattern in pancreatic tumors." (PMID 34944918, 2021). "In contrast, a study focused on pancreatic cancer models found that Klotho overexpression or treatment with sKL reduced the growth of pancreatic cancer cell lines and xenografts, and inhibited FGF pathway signalling, resulting in reduced cell proliferation." (PMID 32585905, 2020). "They undertook IHC analysis of Klotho protein expression in 18 pancreatic cancer tissues and found that 83% (15/18) displayed reduced Klotho expression compared with normal human kidney sections (p = 0.002)." (PMID 32585905, 2020). "In Colo357, MiaPaCa2, and Panc1 pancreatic cancer cells, the investigators confirmed epigenetic silencing through promoter methylation of the KLOTHO gene." (PMID 32585905, 2020). "Further, pancreatic cancer cells transfected with an HA-tagged Klotho expression vector displayed a reduced number and size of surviving colonies compared with controls." (PMID 32585905, 2020). "For instance, in pancreatic cancer, Klotho was poorly expressed in the tumor." (PMID 35903083, 2022). "Bioinformatics analyses of The Cancer Genome Atlas (TCGA) datasets revealed a correlation between the survival of PDAC patients, levels of klotho expression, and DNA methylation, and demonstrated a unique hypermethylation pattern of klotho in pancreatic tumors." (PMID 34944918, 2021). "In pancreatic cancer, klotho’s downregulation is correlated with patients’ survival." (PMID 34944918, 2021). "In addition, pancreatic cancer mouse xenografts were treated with either Klotho, administered daily by intraperitoneal injection, or vehicle control; the xenograft weight and volume were significantly reduced in the experimental arm." (PMID 32585905, 2020). "In a xenograft model, administration of viral particles carrying sKL, a spliced klotho isoform containing the KL1 domain, inhibited pancreatic tumors." (PMID 34944918, 2021). "Here, we reported the introduction of the active region of klotho (sKL) using the AAV expression system, which resulted in a therapeutic effect in a model of pancreatic cancer." (PMID 34944918, 2021). "A previous study reported that Klotho exerted an inhibitory effect on the IGF-1 pathway in both breast and pancreatic cancer cells." (PMID 25759982, 2015).
rheumatoid arthritis (12 papers, 2009 to 2025). A chronic, systemic autoimmune disorder characterized by inflammation in the synovial membranes and articular surfaces. "A cohort study of patients with rheumatoid arthritis found that elevated Klotho levels within specific ranges (838.81 pg/mL for all-cause mortality and 1061.23 pg/mL for cardiovascular mortality) were associated with a reduced risk of both all-cause and cardiovascular mortality." (PMID 39556550, 2024). "Klotho gene expression is also important in T cells and is correlated to age-related diseases like rheumatoid arthritis (RA)." (PMID 34944847, 2021). "A decrease in the expression of Klotho, observed in DM and DN, was also found in CD4+ lymphocytes (T-helper cells) in healthy elderly individuals and individuals with rheumatoid arthritis, a chronic autoimmune disorder that causes joint inflammation." (PMID 33478014, 2021). "Expressions of β-D-hexosaminidase, β-D-glucuronidase, hyaluronidase, sperm adhesion molecule 1 and klotho genes were measured in synovial fibroblasts and synovial membrane samples of patients with rheumatoid arthritis and osteoarthritis by real-time PCR." (PMID 19442276, 2009). "While it is known that klotho has negative regulatory effects in a variety of diseases such as metabolic disorders and kidney disease, the specific role of klotho in rheumatoid arthritis (RA) and its effect on mortality are unclear." (PMID 37587536, 2023).
Osteopenia (11 papers, 2014 to 2025). Osteopenia is a term to define bone density that is not normal but also not as low as osteoporosis. "Klotho is known as the anti-aging protein and klotho-deficient mice have low bone formation and bone resorption, leading to a low bone turnover osteopenia." (PMID 35011173, 2021). "Klotho is a powerful longevity protein that has been linked to the prevention of muscle atrophy, osteopenia, and cardiovascular disease." (PMID 24987372, 2014). "Bone histology of klotho deficient mice previously revealed the osteopaenia to be caused by cortical thinning of long bone diaphyses, whereas the epiphyses may paradoxically have an increased BMD and trabecular bone volume." (PMID 25860694, 2015). "The serum Klotho protein level in the group with lumbar vertebral osteopenia was clearly lower than that of the group with a normal bone mass in the lumbar vertebrae." (PMID 29665846, 2018). "Similarly, serum Klotho protein levels were significantly lower in those with lumbar spinal osteopenia as compared with those in the normal group." (PMID 29665846, 2018).
end-stage renal disease (10 papers, 2013 to 2025). "An increase in serum Klotho protein levels may decrease the risk of CKD-MBD and low BMD in patients with end-stage renal diseases." (PMID 29665846, 2018).
uremia (10 papers, 2013 to 2024). A clinical syndrome associated with the retention of renal waste products or uremic toxins in the blood. "The FGF23–Klotho axis emerges as a new therapeutic target to prevent acquired long QT syndrome in uremia by minimizing the predisposition to potentially fatal ventricular arrhythmias and sudden cardiac death in patients with CKD." (PMID 35042527, 2022). "We carried out a translational approach to study the relationship between the FGF23–Klotho signaling axis and acquired long QT syndrome in CKD-associated uremia." (PMID 35042527, 2022). "The expression of the antiaging and renoprotective gene klotho is known to be suppressed under conditions of uremia." (PMID 31354889, 2019). "Normally, FGF23 decrease PTH gene expression and parathyroid cell proliferation 64, 65, however, hyperplastic parathyroid glands in uremia patients resist to FGF23 inhibitory action due to low expression of both klotho and FGF 23-receptor complex 66-68." (PMID 31839746, 2019). "In addition, uremic toxins have been suggested to contribute to CI by inducing metabolic changes that eventually lead to apoptotic death in neuronal cells; in parallel, uremia has been demonstrated to contribute to Klotho down-regulation through epigenetic mechanisms." (PMID 38673780, 2024). "However, animal studies have shown that parathyroid Klotho secretion decreased in uremia, suggesting that secretion may be reduced in all organs in uremia, but further studies are needed." (PMID 34079811, 2021). "Thus, inhibition of KL gene expression correlates with gene hypermethylation, suggesting that epigenetic modification of KL gene may be an important pathological mechanism of uremia." (PMID 24224012, 2013). "Klotho function could also be affected by HMG-CoA reductase inhibitors, uremia-related compounds, or demethylation agents." (PMID 35004821, 2021).
acromegaly (9 papers, 2014 to 2024). Acromegaly is an acquired disorder related to excessive production of growth hormone (GH) and characterized by progressive somatic disfigurement (mainly involving the face and extremities) and systemic manifestations. "Soluble Klotho concentrations appear to be a useful marker of QoL in acromegaly patients but the underlying mechanisms remain to be investigated." (PMID 32333268, 2020). "Soluble Klotho concentrations appear to be a useful marker of QoL in acromegaly patients, but the underlying mechanisms have to be investigated." (PMID 32333268, 2020). "Recent data also indicated an association between klotho levels and growth hormone (GH) levels in acromegaly." (PMID 25198618, 2014). "The klotho gene encodes a transmembrane protein (mKL) expressed mainly in the kidneys and the soluble part, soluble alpha klotho (sKL), has been investigated as potential new marker in acromegaly." (PMID 39202522, 2024). "In acromegaly, increased levels of circulating klotho have been reported, returning to normal values shortly after surgery." (PMID 33776931, 2021). "Only in one study on acromegaly patients it was shown that serum Klotho levels were higher in women than in men." (PMID 34670596, 2021). "Two recent studies in patients with acromegaly demonstrated increased blood levels of klotho which returned to normal after normalization of GH and IGF-1 levels, suggesting that klotho expression or secretion is regulated by GH or IGF-I." (PMID 25198618, 2014). "Soluble Klotho concentrations may be a new useful marker of QoL in acromegaly patients which should be further studied." (PMID 32333268, 2020). "However, GH also exerts influences on Klotho levels, as patients with acromegaly show increased levels of Klotho, and they show a downregulation when the GH-produced pituitary adenoma is removed." (PMID 32230747, 2020). "Recent data suggest that the increase in serum phosphate under GH treatment or acromegaly is unexpectedly associated with upregulation of the phosphaturic FGF23/Klotho axis, suggesting counter-regulatory mechanisms or an FGF23 resistance induced by GH-stimulated Klotho secretion in the kidney." (PMID 34199514, 2021). "In addition, Klotho might be a link between GH/IGF-1, inflammation and metabolic dysregulation in acromegaly, since Klotho impacts on all these components." (PMID 32458292, 2020). "Klotho protein has been proposed as a clinical biomarker for GH/IGF status, i.e., in the diagnosis and treatment of acromegaly." (PMID 35434614, 2022). "However, in adults with acromegaly positive correlations between IGF-I and klotho have been reported." (PMID 35434614, 2022).
glomerulosclerosis (9 papers, 2019 to 2026). A hardening of the kidney glomerulus caused by scarring of the blood vessels. "Moreover, CKD exhibits many features of aging, including glomerular sclerosis and interstitial fibrosis, loss of Klotho, local RAS activation, increased oxidative stress, and persistent inflammation." (PMID 31318148, 2019). "Klotho acts as an antagonist of the Wnt/β-catenin pathway, which is involved in the pathogenesis of proteinuria, glomerulosclerosis and tubulointerstitial fibrosis." (PMID 41596204, 2026). "Resveratrol treatment has been demonstrated to reduce renal oxidative stress and prevent Con A-induced progressive glomerulosclerosis through SIRT1-mediated Klotho expression in old mice." (PMID 38069234, 2023). "Compared with the db/db animals exposed to Ad-NC, the animals challenged with Ad-KL showed ameliorated glomerulosclerosis, decreased podocyte foot process effacement, elevated Synaptopodin expression, and more cells positive for WT-1 in the kidneys." (PMID 35480629, 2022). "This is consistent with a previous report that soluble klotho reduces glomerulosclerosis in part by the suppression of TRPC6 expression on the podocyte cell surface." (PMID 33918778, 2021). "The roles of klotho and oxidative stress in glomerulosclerosis were further supported by in vitro studies using mesangial cells treated with resveratrol and/or via the silencing of klotho prior to Con A challenge." (PMID 32942691, 2020). "Subsequently, we decreased the klotho levels using siRNA to confirm a direct relationship between klotho, glomerulosclerosis, and oxidative stress and Con A challenge." (PMID 32942691, 2020). "Several animal studies demonstrated that SAC effectively decreased urinary IS levels, ameliorated renal dysfunction, increased renal klotho expression, and mitigated pathological changes such as glomerular hypertrophy, glomerulosclerosis, interstitial fibrosis, and proteinuria." (PMID 41007509, 2025). "The downregulation of Klotho expression, which promotes glomerulosclerosis and renal tubulointerstitial fibrosis, may be a contributing factor to this phenomenon." (PMID 37362429, 2023). "Furthermore, in kidney mesangial cells, klotho silencing abolished the effects of resveratrol on the Con A-mediated elevation of the indices of oxidative stress and the expression of glomerulosclerosis-related factors." (PMID 32942691, 2020). "To partially address these limitations, we used mouse kidney mesangial cells to demonstrate the mechanism of the inhibitory effect of resveratrol pretreatment against Con A-induced increases of ROS and glomerulosclerosis-related factor expression through the downregulation of the klotho level." (PMID 32942691, 2020). "From the functional results, whether Xing or Yao ‘s experiments, Klotho intervention can significantly reduce the apoptosis rate of podocytes, improve urinary albumin excretion, and slow down glomerulosclerosis and renal function deterioration in animal models." (PMID 41438297, 2025). "Our data indicated that resveratrol pretreatment protected against Con A-induced advanced glomerulosclerosis in aged mice by attenuating renal oxidative stress, at least in part, through SIRT1-mediated klotho expression." (PMID 32942691, 2020). "Therefore, we speculate that Con A-induced severe albuminuria and advanced glomerulosclerosis are highly correlated with increased renal oxidative stress via the repression of SIRT1-mediated klotho expression and that these effects are attenuated by resveratrol pretreatment." (PMID 32942691, 2020). "The overexpression of glutathione peroxidase-1, one of the most important antioxidant enzymes, in aged kidneys was found to independently reduce glomerulosclerosis and interstitial fibrosis in old mice through antioxidant activity with NRF2 and Klotho signaling." (PMID 38069234, 2023).